PI4KA (phosphatidylinositol 4-kinase alpha)
Description:
Acts on phosphatidylinositol (PtdIns) in the first committed step in the production of the second messenger inositol-1,4,5,- trisphosphate.
Synonyms: PI4K-alpha; PIK4CA; pi4K230; GIDID2; PMGYCHA; SPG84
Tractability: Small molecule: a structure with a bound ligand is known; a high-quality ligand is known. Antibody: UniProt places it where antibodies can reach, with high confidence; its Gene Ontology location is reachable by antibodies, with high confidence; the Human Protein Atlas places it where antibodies can reach. PROTAC: ubiquitination databases record sites on it; its protein half-life has been measured; a small molecule that binds it is known.
Target class: Enzyme; Transferase
Gene: Protein-coding gene on chromosome 22 (20,707,691 to 20,859,417, reverse strand). Ensembl gene ENSG00000241973.
Subcellular location: Cytoplasm; Cell membrane
Subcellular location (Human Protein Atlas): Nucleoplasm; Plasma membrane
Pathways (Reactome):
Metabolism: Synthesis of PIPs at the ER membrane; Synthesis of PIPs at the Golgi membrane
Gene Ontology:
Molecular function: 1-phosphatidylinositol 4-kinase activity; cadherin binding; protein binding; kinase activity
Biological process: host-mediated perturbation of viral process; phosphatidylinositol phosphate biosynthetic process; reorganization of cellular membranes to establish viral sites of replication; phosphatidylinositol biosynthetic process; phosphatidylinositol-mediated signaling; signal transduction; myelination in peripheral nervous system
Cellular component: cytoplasm; extracellular exosome; focal adhesion; membrane; plasma membrane; cytosol; Golgi-associated vesicle membrane
Genetic constraint (gnomAD): Loss-of-function variants: 89 observed, 193.86 expected, observed/expected ratio (o/e) 0.46, 90% interval 0.39 to 0.55. The upper end of that interval is the gene's LOEUF score, 0.55, which puts it in group 2 of 6, group 1 being the genes least tolerant of losing a copy. Missense variants: 1,638 observed, 2,239.9 expected, observed/expected ratio (o/e) 0.73, 90% interval 0.7 to 0.76. Synonymous variants: 893 observed, 889.89 expected, observed/expected ratio (o/e) 1, 90% interval 0.95 to 1.06.
Homologues: Orthologues: macaque PI4KA (99% identical), dog PI4KA (97% identical), rat Pi4ka (97% identical), mouse Pi4ka (95% identical), pig PI4KA (95% identical), rabbit PI4KA (94% identical), guinea pig PI4KA (94% identical), tropical clawed frog pi4ka (88% identical), chimpanzee PI4KA (84% identical), zebrafish pi4kaa (81% identical), Drosophila melanogaster Pi4KIIIalpha (47% identical), zebrafish pi4kab (40% identical), and 1 more. Paralogues in human: PI4KB (12% identical), PIK3C2B (12% identical), PIK3C2A (12% identical), PIK3CD (10% identical), PIK3CG (10% identical), PIK3CB (9% identical), PIK3C2G (9% identical), PIK3CA (9% identical), PIK3C3 (6% identical).
Diseases named in the same sentence as PI4KA in open-access papers:
PI4KA is named in the same sentence as 83 diseases in open-access papers, as found by Europe PMC text mining. Sharing a sentence is not in itself a finding about the gene and the disease. The quoted sentences say what the papers report.
schizophrenia (14 papers, 2009 to 2023). A major psychotic disorder characterized by abnormalities in the perception or expression of reality. "Previous studies have suggested that PI4KA is a candidate gene for schizophrenia susceptibility and plays an important role in early brain development." (PMID 37107637, 2023). "The locus of PI4KA is located on chromosome 22q11, which has been suggested to be strongly associated with schizophrenia." (PMID 34361045, 2021). "In a Dutch genetic association study of 310 cases and 880 controls, association analysis of 138 myelin-related genes using 771 SNPs demonstrated that SNPs of PI4KA are the SNPs most significantly associated with schizophrenia." (PMID 34361045, 2021). "Among the PI4KA SNPs associated with schizophrenia, only one, rs165793, was included in our current study, but it did not have a significant effect on PIK4CA protein expression in the postmortem brain." (PMID 34361045, 2021). "PI4KA located at 22q11.2 deletion region repeatedly linked to schizophrenia other psychiatric diseases." (PMID 25025909, 2014). "Moreover, the PI4KA polymorphism, PI4KA-rs165854, has the potential to jointly modulate schizophrenia patients with poor antipsychotic response." (PMID 36341355, 2022). "PI4KA has been associated with schizophrenia susceptibility." (PMID 30614210, 2019). "PIP4K2A and PI4KA have been suggested as putative susceptibility genes on both positional and functional grounds as these are part of phosphoinositide signaling pathway which is implicated in schizophrenia etiology and may modulate antipsychotic response." (PMID 25025909, 2014). "For PI4KA we did identify two rare non-synonymous positions (rs61752248 in two patients and previously unannotated chr22:21081649 G>C in a single patient with schizophrenia)." (PMID 27274857, 2016). "In the present study we investigated the possible association of polymorphisms from five candidate genes RGS4, SLC6A3, PIP4K2A, BDNF, PI4KA with response to antipsychotic in variably ill schizophrenia patients." (PMID 25025909, 2014). "Moreover, the SNP rs1468412 showed a synergistic effect with the SNP rs165854 within phosphatidylinositol 4-Kinase Alpha (PI4KA) gene influencing antipsychotic response in low-severity schizophrenia patients of Indian origin." (PMID 31040787, 2019). "With this background, in the present study, we investigated 53 polymorphisms from five genes (RGS4, SLC6A3, PIP4K2A, BDNF and PI4KA) in 423 south Indian schizophrenia cases segregated into low and high severity of illness to assess their influence on antipsychotic response." (PMID 25025909, 2014).
hepatoma (6 papers, 2011 to 2022). "Overexpression of PI4KA is associated with a poor prognosis of human hepatocellular carcinoma, suggesting that PI4KA may have an underappreciated function in the constitutive chemoresistance of cancers recalcitrant to apoptotic induction." (PMID 36276647, 2022). "In this study, we used a T7 RNA polymerase-based expression system in Huh7 human hepatoma cells to study the roles of PI4KA and PI4KB on HCV membranous web assembly." (PMID 22022594, 2011). "We recently established a drug regimen based on pharmacological inhibition of PI4KA and CKIα (designated PCi) enhancing RNA replication of gt1b WT isolates by approximately 100-fold, allowing infection of Huh7 hepatoma cells with several patient-derived gt1b sera." (PMID 35763545, 2022). "Another recent study has shown that adaptive mutations could prevent a cellular lipid kinase, phosphatidylinositol 4-kinase IIIα (PI4KA) activation, which create a permissive membrane microenvironment in hepatoma cells." (PMID 32714881, 2020). "As observed for PI4KA, it is also possible that the effects of CypA we observe in the hepatoma lines tested may differ in a primary hepatocyte context and/or with the use of patient HCV isolates." (PMID 31074414, 2019).
arthrogryposis (4 papers, 2015 to 2022). A rare, non-progressive congenital disorder characterized by multiple joint contractures which are present at birth. "Also, compound heterozygous mutations in the PI4KA gene were identified in tissue samples from three fetuses with multiple congenital abnormalities, conceived by unrelated parents of European descent, with perisylvian polymicrogyria (PMG), cerebellar hypoplasia, and arthrogryposis." (PMID 30614210, 2019).
hypomyelinating leukodystrophy (4 papers, 2021 to 2025). "AR mutations in PI4KA cause a variable phenotypical spectrum ranging from severe neurodevelopmental disorder with spasticity, hypomyelinating leukodystrophy, and brain abnormalities (NEDSPL) to pure spastic paraplegia type 84 (SPG84)." (PMID 38003592, 2023). "Here we show that biallelic PI4KA sequence alterations in humans are associated with neurological disease, in particular hypomyelinating leukodystrophy." (PMID 34415310, 2021). "Bi‐allelic variants in PI4KA were recently associated with neurodevelopmental disorders (NDD), brain malformations, leukodystrophy, primary immunodeficiency, and inflammatory bowel disease." (PMID 35880319, 2022).
developmental delay (3 papers, 2019 to 2025). "The second most poorly predicted diagnosis was PI4KA in P5, a patient presenting with global developmental delay, poor coordination, hypotonia, and spasticity, with an MRI-brain demonstrating cerebral hypomyelination and a dysplastic corpus callosum." (PMID 38685113, 2024). "Many of these genes have been previously implicatedwith human phenotypes, including developmental delay (e.g. ASPM, AFF3 and MAPT) and intellectual disability (e.g. NEMF, PI4KA and KANSL1)." (PMID 31757203, 2019).
glioma (3 papers, 2023 to 2026). A benign or malignant brain and spinal cord tumor that arises from glial cells (astrocytes, oligodendrocytes, ependymal cells). "In this study, we found that phosphatidylinositol 4-kinase α (PI4Kα) (a subtype of PI4Ks) was downregulated in both low- and high-grade glioma tissues from clinical patients." (PMID 42103227, 2026).
prostate carcinoma (3 papers, 2023). A carcinoma that arises from epithelial cells of the prostate gland. "Using a clinical resource, we demonstrate that PI4KA expression in human prostate cancer bone metastatic biopsies is associated with poor overall survival." (PMID 37996444, 2023). "Our previous study demonstrates that PI4KA expression is higher in metastasis compared to primary prostate cancer and in addition we showed that PI4KA expression is higher in metastasis with matched primary cancer tissue from patients." (PMID 37996444, 2023). "SILAC-based quantitative proteomic analysis of lipid raft microdomains identified phosphatidylinositol 4-kinase III-alpha (PI4KA) as a novel downstream modulator of CXCL12/CXCR4 signaling in prostate cancer cells." (PMID 38239314, 2023). "The selective presence of immunosuppressive cells in high PI4KA-expressing tumors implies that PI4KA activity contributes to tumor growth, and anti-PI4KA therapies have the potential to reverse suppressive phenotype in metastatic prostate cancers." (PMID 37996444, 2023). "Lipid kinase PI4KA identified as a novel target downstream of CXCR4 in prostate cancer cells and in PC cells chemokine signaling induces PI4KA activation for PI4P production at PM." (PMID 38239314, 2023). "The CXCL12/CXCR4 axis has previously been shown to be involved in prostate cancer cell homing to bone tissue, and new investigations found a novel interaction of Phosphatidyl Inositol 4 kinase IIIa (PI4KA) downstream of chemokine signaling." (PMID 38239314, 2023). "PI4KA is highly expressed in prostate cancer metastasis thus, knockdown in prostate cancer cells leads to significant inhibition of on bone tumor growth." (PMID 37996444, 2023). "Here we provided the clinical significance of PI4KA expression in prostate cancer." (PMID 37996444, 2023). "In prostate cancers, PI4KA is overexpressed in metastasis and several chemokine receptors are shown to interact with EFR3 and TTC7 suggesting this interaction brings PI4KA to the PM upon chemokine signaling and contributing to the prostate cancer cell invasion and metastasis." (PMID 38239314, 2023).
Ataxia (2 papers, 2022 to 2023). Ataxia refers to impaired coordination of voluntary muscle movement. "This spectrum of movement disorders was also observed in patients with PI4KA deficiency, including dystonia, spastic paraplegia, opisthotonus, ataxia, and myoclonus." (PMID 35880319, 2022). "We also observed that the level of LMNB1, which is involved in cerebellar ataxia and adult autosomal dominant leukodystrophy (r2 = −0.634, p < 0.0001), and the level of Pi4KA (r2 = −0.634, p = 0.066) in the hippocampus were correlated with the DI." (PMID 37063368, 2023).
bone tumor (2 papers, 2023). "Luciferase imaging of bone tumors show that tumor growth is significantly inhibited (p < 0.05 for #27 and p < 0.01 for #30 PI4KA shRNA) in both PI4KA shRNA knock down cells over scr shRNA infected cells." (PMID 37996444, 2023). "As prior data show that PI4KA expression is significantly higher in mHSPC samples, and its expression contributes to intraosseous growth in intratibial bone tumor model probably through the activation of tumor cell proliferative pathways in mHSPC." (PMID 37996444, 2023). "Thus, to determine the role of PI4KA in CXCL12/CXCR4 signaling contributing to bone tumor growth, we have developed stable knockdown of PI4KA in PC3-CXCR4 and C4-2B cell with two independent PI4KA shRNA (#27 and #30) through lentiviral transduction." (PMID 37996444, 2023). "Using metastatic biopsy sequencing, we found PI4KA expression in tumors correlated with overall survival and contributes to immunosuppressive bone tumor microenvironment through preferentially enriching non-activated and immunosuppressive macrophage populations." (PMID 36865146, 2023).
epilepsy (2 papers, 2022 to 2025). A brain disorder characterized by episodes of abnormally increased neuronal discharge resulting in transient episodes of sensory or motor neurological dysfunction, or psychic dysfunction. "There is a remarkable overlap in the phenotypes of patients with pathogenic variants in PI4KA and PI4K2A, namely brain malformations, epilepsy and movement disorders." (PMID 35880319, 2022). "For example, mental retardation in SPG15/ZFYVE26 and SPG46/GBA2, cognitive impairment and epilepsy in SPG35/FA2H and SPG84/PI4KA." (PMID 39932116, 2025).
hepatitis C (2 papers, 2020 to 2021). "The enzyme exists as a large, 700-kD multi-subunit complex; however, the isolated carboxy-terminal fragment containing the helical and catalytic domain (PI4KAC1001) retains activity and can complement hepatitis C proliferation in PI4KA knockdown cells." (PMID 32211893, 2020). "Indeed, monotreatment with a PI4KA inhibitor developed for the treatment of Hepatitis C infection exhibited acute toxicity in mice." (PMID 34504076, 2021).
Immunodeficiency (2 papers, 2021 to 2022). Failure of the immune system to protect the body adequately from infection, due to the absence or insufficiency of some component process or substance. "The same homozygous c.4867T>G; p.(Tyr1623Asp) PI4KA alteration was subsequently detected by trio WGS in an infant of Amish ancestry who died at 3 weeks from MIA and severe immunodeficiency (Family 1-X:1)." (PMID 34415310, 2021).
leukemia (2 papers, 2022 to 2023). A malignant (clonal) hematologic disorder, involving hematopoietic stem cells and characterized by the presence of primitive or atypical myeloid or lymphoid cells in the bone marrow and the blood. "Meanwhile, clinical sample database analysis has shown that high expression of PI4KA was associated with decreased overall survival of leukemia patients." (PMID 36276647, 2022). "We conducted quantitative proteomic analysis in paired K562/Adr and PI4KA knockout K562/Adr cell lines to explore the molecular mechanism underlying the PI4KA regulation of chemoresistance in leukemia." (PMID 36276647, 2022). "Additionally, the elevated expression of PI4KA was significantly associated with decreased overall survival of leukemia patients." (PMID 36276647, 2022). "To ascertain whether PI4KA expression was associated with chemoresistance in leukemia, we used PI4KA sgRNAs to knock out the PI4KA gene in K562/Adr cells using CRISPR/Cas9." (PMID 36276647, 2022). "We found that PI4KA mRNA levels in BM of patients with relapsed leukemia were significantly higher than those in newly diagnosed leukemia." (PMID 36276647, 2022). "Knocking out PI4KA also decreased mitochondrial membrane potential in drug-resistant leukemia cells." (PMID 36276647, 2022). "In this study, we first identified PI4KA as a novel target that overcomes chemoresistance in leukemia." (PMID 36276647, 2022). "In contrast to leukemia-sensitive cells, the expression of PI4KA at protein and mRNA levels was significantly upregulated in leukemia-resistant cell lines." (PMID 36276647, 2022). "We screened 9 compounds in resistant leukemia cells and normal PBMCs to obtain a high-efficiency and low-toxicity PI4KA inhibitor." (PMID 36276647, 2022). "The R2 genomic analysis indicated that the mRNA expression of PI4KA was significantly upregulated in leukemia patient datasets compared to the normal leukocytes/control dataset." (PMID 36276647, 2022). "In summary, we revealed a novel mechanism supporting the critical role of PI4KA in overcoming chemoresistance in leukemia." (PMID 36276647, 2022). "The potential prognostic value of PI4KA expression for leukemia patients was explored by using the R2, TCGA, and GEO databases." (PMID 36276647, 2022). "We also examined PI4KA expression at protein and mRNA levels in leukemia- sensitive cells (K562, HL-60) and multidrug-resistant cells (K562/Adr and HL-60/Adr)." (PMID 36276647, 2022). "Our study highlighted the potential of therapeutic targeting of PI4KA to overcome chemoresistance in leukemia." (PMID 36276647, 2022). "Depletion of PI4KA sensitized drug-resistant leukemia cells to chemotherapeutic drugs in vitro and in vivo by regulating ERK/AMPK/OXPHOS axis." (PMID 36276647, 2022). "Our findings suggest that a combination of PI4KA inhibitor with classic chemotherapeutic agents could be a novel therapeutic strategy for treating drug-resistant leukemia." (PMID 36276647, 2022). "We subsequently assessed whether PI4KA knockout could inhibit leukemogenesis in vivo by using the drug-resistant leukemia xenograft mouse model." (PMID 36276647, 2022). "Our findings also suggested that combining a PI4KA inhibitor with classic chemotherapeutic agents could represent a novel therapeutic strategy for treating refractory leukemia." (PMID 36276647, 2022). "We hypothesized that PI4KA regulates chemoresistance in leukemia, and inhibition of PI4KA activity may reverse chemoresistance in leukemia cells based on the following observations." (PMID 36276647, 2022). "Thus, our findings indicated that inhibition of PI4KA activity appears essential for chemoresistance in leukemia cells." (PMID 36276647, 2022). "We also discovered that cepharanthine (CEP), a novel PI4KA inhibitor, could enhance the sensitivity of drug-resistant leukemia cells to chemotherapeutic drugs in vitro and in vivo." (PMID 36276647, 2022).